VTN (vitronectin)
Diseases named in the same sentence as VTN in open-access papers (continued):
Sharing a sentence is not in itself a finding about the gene and the disease.
tumor (continued). "PAI-1 is known to play a vital role in the pathogenesis of cancer, as it inhibits proteolysis, blocks apoptosis, increases tumor cell adhesion, binds with vitronectin and interacts with integrins, promotes tumor cell proliferation, and affects angiogenesis." (PMID 29988148, 2018). "VTN can affect tumor cell adhesion, motility, invasion, and proliferation, in addition to protecting tumor cells from apoptosis-related cell death." (PMID 29568064, 2018). "We chose to focus on the basement membrane proteins laminin and fibronectin, and vitronectin which has been shown to be expressed at the leading edge of the tumour, to elucidate their roles in GSC migration and differentiation." (PMID 27541285, 2017). "αvβ5 was localized on the membrane of tumor cells while vitronectin was seen exclusively in the stroma surrounding the blood vessels." (PMID 27484721, 2016). "This egress is mediated by the random chemokinetic effect of vitronectin on cancer cells that leave an expanding tumor." (PMID 27634880, 2016). "While the increased expression of VCAM1 promotes tumor invasion and metastasis, high levels of VTN and/or FN1 in circulation have been reported to promote tumor formation and metastasis." (PMID 26930275, 2016). "In vitro experiments indicated that uPAR mediates tumour cell adhesion by interacting with mesothelial vitronectin." (PMID 27074785, 2016). "Our in vitro data demonstrated further enhanced EGFRvIII activity and tumor cell invasion in the tumor microenvironment of hypoxia plus extracellular matrix (ECM) vitronectin, in which EGFRvIII and integrin β3 tended to form complexes." (PMID 26717039, 2016). "The stretching of fibronectin coupled with the availability of vitronectin in the tumor stroma creates a specialized niche to protect tumor cells from therapies designed to activate extrinsic cell death pathways." (PMID 27484721, 2016). "FN1, SPP1, CXCL12 and vitronectin (VTN) are known to promote the survival and migration of tumor cells." (PMID 27329720, 2016). "Taken together, the data are consistent with a model whereby tumor cells proximal to both fibronectin and vitronectin within the stromal matrix represent a cohort of TRAIL-resistant cells." (PMID 27484721, 2016). "Binding of SERPINE1 to vitronectin results in detachment of the tumor cell from the extracellular matrix (ECM), leading to enhanced mobility of the cells." (PMID 26286584, 2015). "The lectin promotes adhesion of neutrophils to laminin and fibronectin and enhances the adhesion of a tumor cell line to these molecules as well as to vitronectin." (PMID 24049657, 2013). "The doxycycline-induced PAI-1 pool anti-angiogenic effect is due to an early wave of apoptosis in tumor ECs and this effect was described as vitronectin-dependent." (PMID 22563394, 2012). "PG affects the levels of several ECM molecules, including down-regulation of vitronectin, which is instrumental in tissue invasion, metastasis, and tumor formation." (PMID 22860065, 2012). "FACS analysis for αv, α5 and β1 integrin subunits showed little difference in expression between cells from tumour and normal tissue, suggesting αvβ3 is responsible for tumour cell migration towards and adhesion to vitronectin." (PMID 24213501, 2012). "Vitronectin is substantially enriched at sites of injured, fibrosing, inflamed, and tumor tissues where it is believed to be involved in wound healing and tissue remodeling." (PMID 21573223, 2011). "On the other hand, vitronectin also stimulates tumor invasiveness and contributes to the development of chronic tissue injuries." (PMID 21573223, 2011). "Unlike in quiescent EC, the αvβ3 integrin is highly expressed by tumor EC, which helps the binding of new ECs to the provisional matrix components, including vitronectin and fibronectin that are deposited in the tumor microenvironment." (PMID 22069567, 2010). "Tumour cell vitronectin adhesion and in vitro ECM invasion were likewise consistently amplified with LPS challenge." (PMID 19436306, 2009).
tumor (continued). "In vitro tumour cell vitronectin adhesion and ECM invasion were analysed by vitronectin adhesion assay and ECM invasion chambers." (PMID 19436306, 2009). "It has recently been shown that matrix metalloproteinase (MMP)-2 secreted by tumour cells degrades vitronectin and produces fragmented vitronectin, which is more potent than its naïve form in promoting adhesion and migration of cancer cells." (PMID 19400944, 2009). "LPS upregulates u-PA and u-PAR in a dose-dependent manner, enhancing in vitro tumour cell vitronectin adhesion and ECM invasion by >40% (P<0.01)." (PMID 19436306, 2009). "TLR-4 blockade also significantly reduced LPS-dependent tumour cell vitronectin adhesion and in vitro tumour cell invasion for SW480 and SW620 cell lines." (PMID 19436306, 2009). "Tumour-infiltrating lymphocytes migrated towards soluble vitronectin by chemotaxis at low concentrations and at higher concentrations stimulated chemokinesis." (PMID 17088900, 2006). "In contrast, vitronectin and infiltrating lymphocytes were detected both in peritumoural stroma and within the tumour itself, including on tumour vessels in HCC, where vitronectin is probably secreted by malignant hepatocytes." (PMID 17088900, 2006). "Next, we demonstrated that vitronectin within tumour tissue can support lymphocyte adhesion using a modified Stamper–Woodruff tissue-binding assay on tissue sections of tumours." (PMID 17088900, 2006). "Tumour-infiltrating lymphocyte adhesion to these vitronectin-rich regions was significantly inhibited by a function blocking antibody against vitronectin." (PMID 17088900, 2006). "Tumour-infiltrating lymphocytes preferentially bound to stromal areas where strong expression of vitronectin was detected." (PMID 17088900, 2006). "A trend towards increased vitronectin adhesion with increasing tumour grade was apparent, with both grade 3-derived cell lines, MiaPaCa-2 and Panc-1, attaching strongly to vitronectin." (PMID 16622460, 2006). "The 3D structure of VTN indicated the presence of specific functional domains that could be involved in tumor-related interactions." (PMID 40433359, 2025). "Moreover, VTN interacts with integrins on the surface of tumor cells to ward off apoptotic signals, fostering cell survival and proliferation, thereby expediting tumor progression." (PMID 40433359, 2025). "This genome-wide CRISPR screen showed that blocking the vitronectin (Vtn)-complement C1Q binding protein (C1qbp) interaction could increase macrophage phagocytosis, inhibiting tumour progression in vivo." (PMID 40650785, 2025). "Importantly, our in vivo data suggest that VTN overexpression synergistically enhances anti-tumor response with anti-PD1, providing functional validation of its immune-potentiating effects." (PMID 40433359, 2025). "The observed positive correlation between VTN and immunostimulants such as CXCL12, a chemokine critical for T cell recruitment, potentially suggests that overexpression of VTN may trigger an enhanced anti-tumor immune response in tumors." (PMID 40433359, 2025). "THL has been shown to inhibit adhesion to vitronectin and tumor-induced angiogenesis in vivo by decreasing paxillin in human umbilical vein endothelial cells (HUVECs); and to block Hsp27 phosphorylation by inducing endothelial cell adhesion and wound/tumor-driven angiogenesis in vitro." (PMID 41035918, 2025). "Functional experiments further support this hypothesis: cancer cell-intrinsic VTN knockdown enhanced proliferation, invasion, and migration, while overexpression suppressed tumor growth and synergized with anti-PD1 therapy." (PMID 40433359, 2025). "Additionally, CRC organoids isolated from fresh tumor tissues exhibited increased numbers and volumes following treatment with rhVTN or overexpression of VTN." (PMID 40538300, 2025).
tumor (continued). "Vitronectin (VTN) promotes tumour cell migration and invasion by enhancing adhesion to the stroma and interactions with cell surface integrins, possibly supporting tumour nutrient and oxygen supply by influencing vascular endothelial function and promoting neointimal formation." (PMID 39944086, 2025). "Furthermore, mice with VTN-overexpressed tumors treated with anti-PD1 agents showed a considerable slowdown in tumor growth compared to those receiving anti-PD1 treatment or VTN overexpression independently." (PMID 40433359, 2025). "The 2D structure showed that VTN is detected in the endoplasmic reticulum and vesicles, and is predicted to be secreted, aligning with its potential role in extracellular matrix remodeling and tumor progression." (PMID 40433359, 2025). "The results indicated that VTN may negatively regulate tumor apoptosis, cell cycle, DNA damage repair, invasion, and stemness, and may positively regulate tumor Angiogenesis, differentiation, hypoxia, apoptosis, apoptosis, and inflammation." (PMID 40433359, 2025). "This hypothesis is functionally supported by our in vivo findings, where VTN overexpression not only suppressed tumor growth but also synergized with anti-PD1 to amplify therapeutic efficacy." (PMID 40433359, 2025). "Restoring VTN expression could disrupt this fibrotic niche, as evidenced by reduced invasion/migration in vitro and delayed tumor progression in vivo, thereby sensitizing tumors to checkpoint blockade." (PMID 40433359, 2025). "From the fundamental perspective, the knockdown of VTN could significantly inhibit the proliferation in cancer cells of liver and the tumor size in xenografts." (PMID 39717749, 2024). "PAI-1 also binds with vitronectin and inhibits the vitronectin-integrin V3 interaction, affecting a cascade of cell functions, such as cell adhesion, migration, proliferation, and apoptosis, depicting the anti-tumor roles of PAI-1." (PMID 39161580, 2024). "VTN can promote tumor growth and metastasis by regulating the EMT process." (PMID 39717749, 2024). "First, the mechanism of action of VTN in tumors is still not fully understood, and its impact on tumor progress is complex and may be regulated by multiple factors." (PMID 39717749, 2024). "A scholar recently found that VTN could induce tumor cell proliferation through the JNK and ERK pathways." (PMID 39717749, 2024). "In addition, the binding of PAI-1 and LRP1 can stimulate vitronectin expression in tumor cells, which further regulates cell motility." (PMID 36605486, 2023). "High expression of FOSB+, NEAT1+, or XIST+ tumor cell-associated genes such as FSTL3, VTN, PAPPA, CCN1, RRAD, and GPRIN3 may predict poor survival in patients with LUSC, suggesting that these genes act as prognosis biomarkers." (PMID 37430270, 2023). "ITGB3 could directly interact with proteins containing RGD (Arg-Gly-Asp) motif, such as fibronectin and vitronectin, which further play essential roles in tumor angiogenesis." (PMID 36130933, 2022). "TGFB1 containing EVs has been reported to bind to the receptors present on the recipient cells and activating SMAD dependent or SMAD independent signaling regulating the expression of oncogenes (PI3K, AKT, N-cadherin, vitronectin, MMPs) and promoting tumor cell proliferation, invasion." (PMID 36505879, 2022). "Indeed, KLK5 has recently been shown to cleave ECM (collagens type I, II, III, IV, fibronectin, and laminin) and adhesion molecules (fibrinogen and vitronectin), suggesting a role in tumor invasion and angiogenesis." (PMID 33588911, 2021). "Fibronectin and vitronectin favor tumor angiogenesis through α5β1 and αvβ3, respectively." (PMID 34308743, 2021). "Furthermore, DNA and 1,2-dioleoyl-3- trimethylammonium propane-bearing lipidic nanoparticles had a high level of vitronectin in human plasma that was readily taken up into tumor tissues bearing the overexpressed receptor vitronectin (integrin αvβ3)." (PMID 34680613, 2021).
tumor (continued). "Conversely, it was also found that PAI-1 could suppress tumor migration by interacting with the binding site between vitronectin and integrin." (PMID 34422809, 2021). "Specifically, MMP-2-catalyzed cleavage of fibronectin (FN) and vitronectin (VN) allows generation of proteolytic fragments with enhanced adhesive properties and may be involved in tumor cell–mesothelial cell adhesion to initiate metastases." (PMID 33810259, 2021). "Roles for VTN in haemostasis and tumour malignancy have also been described." (PMID 31936359, 2020). "NB stiff ECM is rich in cross-linked collagen III fibers, poor in glycosaminoglycans, supporting sinusoidal vascular structures (blood and lymphatic) and with a high quantity of territorial vitronectin (VN, located in the cytoplasmic compartment and in a thin layer around the tumor cells)." (PMID 33109237, 2020). "In vivo experiments revealed tumor cells with high and dense cytoplasmic vitronectin expression." (PMID 31117974, 2019). "Vitronectin may also play a role during intravasation as it can be detected in subendothelial regions and in small vessels surrounding tumor cells." (PMID 29382358, 2018). "Vitronectin connects with assembled matrix proteins around wounds and thus may act as a bridge between the circulating tumor cells and areas of vascular damage." (PMID 29382358, 2018). "Also, treating the cells with the aptamer drastically hampers the αvβ3-mediated cell attachment to vitronectin in vitro and strongly reduced the tumor uptake of the IntegriSense αvβ3-targeting agent, as assessed by in vivo imaging analyses of TNBC xenografts." (PMID 28425453, 2017). "NSCLC human tumor samples were immunostained for vitronectin." (PMID 27484721, 2016). "In addition to regulation of gene expression, plakoglobin has been shown to act as a tumor/metastasis suppressor by modulating Rho, Fibronectin and Vitronectin-dependent Src signaling." (PMID 24260116, 2013). "Although a typical basement membrane matrix has not been described at the interface between xenograft tumor and host brain, reactive astrocytes (fibronectin), and the invading tumor itself (vitronectin, proteoglycans) can both secrete ECM components shared by the Matrigel® substrate." (PMID 22490015, 2012). "Furthermore, plasmin also degrades basement membrane and a broad spectrum of ECM, including fibronectin, vitronectin, and laminin, leading to tumor cell invasion and metastasis." (PMID 21224999, 2011). "In addition, the engineered knottin peptide inhibited tumor cell adhesion to vitronectin, an extracellular matrix protein that binds to αvβ3 and αvβ5 integrins." (PMID 21364742, 2011). "Given the perceived role of vitronectin in cancer, decreased vitronectin levels in serum might be a reflection of increased turnover rate of vitronectin by tumour cells." (PMID 19400944, 2009). "Furthermore, SN-50 pre-treatment attenuated LPS-dependent tumour cell vitronectin adhesion and in vitro ECM invasion compared to cells stimulated with LPS (P<0.05) or LPS plus SN-50M (P<0.05)." (PMID 19436306, 2009). "LPS significantly increased tumour cell vitronectin adhesion." (PMID 19436306, 2009). "Furthermore cycloheximide attenuated LPS-dependent tumour cell vitronectin adhesion and in vitro ECM invasion compared to cells stimulated with LPS alone (P<0.05)." (PMID 19436306, 2009). "Leucocytes may encounter vitronectin either as a soluble protein or immobilised within the extracellular matrix or on tumour vessels." (PMID 17088900, 2006). "Furthermore, we show for the first time that vitronectin can support the adhesion and migration of tumour-infiltrating lymphocytes (TIL)." (PMID 17088900, 2006). "Thus, vitronectin can combine with other adhesive proteins expressed within the tumour microenvironment to support the recruitment and retention of lymphocytes within liver tumours and inflamed liver tissue." (PMID 17088900, 2006).
tumor (continued). "We hypothesised that the extracellular matrix glycoprotein vitronectin, a major component of the stroma of hepatic tumours, might play a role in the recruitment and retention of tumour-infiltrating lymphocytes (TIL)." (PMID 17088900, 2006). "In both HCC and CHM, strong vitronectin staining was detected in the tumour stroma." (PMID 17088900, 2006). "Interestingly, the differences in tumor volume and weight between groups were more pronounced in BALB/c mice than in nude mice, indicating that VTN may promote tumor development through synergistic effects with other immune microenvironment components." (PMID 40538300, 2025). "Therefore, as an essential tumor promoter gene, treatment targeting VTN could be a therapeutic target." (PMID 39717749, 2024). "In this study, we found that the presence of vitronectin-positive blood vessels surrounded by tumor-infiltrating macrophages may play an important role in facilitating the onward spread of tumor cells towards other distant metastatic sites such as the lungs and peritoneum." (PMID 38473429, 2024). "Though other MMPs (e.g., MMP-1, -2, -8, -9, -13) have been linked to degradation of laminin, vitronectin, fibronectin, enactin, collagen I-IV, MMP-10 has been identified as a stromelysin which can degrade various proteoglycan components of the ECM, thus facilitating tumor cell dissociation." (PMID 24885595, 2014). "In the present study, CHM were characterised by a stromal reaction around the tumour, which was heavily infiltrated by lymphocytes associated with strong staining for vitronectin, whereas the tumour itself did not express vitronectin and was largely devoid of lymphocytes." (PMID 17088900, 2006). "Under pathological conditions, tumor cells overexpress αvβ3, and the ECM protein vitronectin promotes metastasis by binding to αvβ3 via its RGD domain and regulating the expression of MMPs through the PI3K signaling pathway." (PMID 41601637, 2026). "Critically, VTN expression correlated with key immunomodulators: positive associations with CXCL12 (a chemokine promoting T-cell recruitment) and negative trends with PD-L1/CTLA4 (immune checkpoint mediators) suggest that VTN may remodel the tumor immune microenvironment." (PMID 40433359, 2025). "Especially complex are processes involving cell adhesion and tumor invasion that include intricate interplay between uPAR, PAI1, uPA, and vitronectin, but also plasminogen and plasmin." (PMID 39859388, 2025). "Following a comprehensive database analysis and validation of tumor tissue samples from CRC patients, we identified VTN as highly expressed in CAFs." (PMID 40538300, 2025). "Additional ARGs, including PDGFA, VTN, and POSTN, revealed intricate and subtype-specific correlations with both macrophages and T cells, reinforcing their involvement in shaping the tumor immune landscape." (PMID 40943183, 2025). "To further elucidate the cellular origin of secreted VTN within the TME, we conducted colocalization analysis using tumor tissue sections from CRC patients." (PMID 40538300, 2025). "In addition, VTN could promote tumor cell growth in a concentration-dependent manner." (PMID 39717749, 2024). "Conversely, a pervasive decrement was witnessed in the expression of GABARAPL1, MAP1LC3C, VTN, and IL6 in nearly all tumor specimens relative to their paired normal tissue counterparts." (PMID 38460947, 2024). "Tumor size-related proteins were involved in angiogenesis (VCAN, VTN, NRP1), EMT (FN1, CD44, THBS2), and translation (EIF1AX, EIF5), further indicating the biological basis of ccRCC growth." (PMID 37460463, 2023). "In tumour samples, the intercellular interactions were mainly active in signalling pathways, including pathways involving SPP1, VTN, NOTCH, THY1, and CD46." (PMID 36860314, 2023). "While the comparison of expression data between tumor and normal samples showed that 8 out of 36 ARGs were significantly differentially expressed, including CCND2, CXCL6, KCNJ8, LPL, SERPINA5, SLCO2A1, VTN, and APOH." (PMID 35836112, 2022).